CD4 (CD4 molecule)
Diseases named in the same sentence as CD4 in open-access papers (continued):
Sharing a sentence is not in itself a finding about the gene and the disease.
AIDS (continued). "AIDS in humans, monkeys and mice infect macrophages and CD4+ T cells, including those that reside in secondary lymphoid organs, such as lymph nodes and spleen." (PMID 35203323, 2022). "This late presentation refers to individuals showing up for HIV care with a CD4 count below 350 cells/μl or with an AIDS‐defining event." (PMID 34554647, 2022). "In 1996, combination antiretroviral therapy (ART) was provided free of charge to PWH with a CD4 cell count < 200 cells/μL or an AIDS-defining illness according to CDC 1993 criteria." (PMID 35581552, 2022). "Nevertheless, approximately 10%–40% of people living with HIV/AIDS (PLWH) are unable to achieve optimal CD4+ T-cell recovery despite virological suppression under the combined antiretroviral therapy (cART)." (PMID 35154126, 2022). "A high percentage of patients with AIDS (85.4%) and with CD4 lymphocyte counts < 200/mm were detected (88.9%), suggesting that this population is at high risk for AIDS-associated diseases." (PMID 36123430, 2022). "Low CD4/CD8 ratios are associated with increased risks of morbidity and mortality, and are prognostic of non-AIDS defining events in HIV-1-infected individuals." (PMID 34983415, 2022). "AIDS is the stage of a human immunodeficiency virus (HIV) infection in which the level of CD4 + T lymphocytes is lower than the critical level." (PMID 35214519, 2022). "Meanwhile, HIV infection leads to Acquired immunodeficiency syndrome (AIDS) when CD4 T cells are reduced below 200 cells per liter of blood." (PMID 35600204, 2022). "After the heterologous SIV challenge, vaccinated macaques showed greater and earlier viremia than control macaques, as well as a faster decline in CD4+ T cell number and accelerated AIDS progression." (PMID 36033843, 2022). "Regarding the severity of the disease, 85.5% had a clinical stage of AIDS, 88.9% had a CD4 lymphocyte count < 200 mm3, and 91.7% had a viral load ≥ 50 mm3." (PMID 36123430, 2022). "Because of the decreased CD4+ T cells, the immune function of AIDS patients is declined, and thus the ability to clear PJ in the alveoli is reduced, allowing it to multiply in the alveoli." (PMID 35130846, 2022). "Human Immunodeficiency Virus (HIV) infection results in many cases in acquired immunodeficiency syndrome (AIDS), which is characterized by depletion of CD4+ white blood cells." (PMID 35736971, 2022). "Oral manifestations are early and important clinical indicators of Human Immunodeficiency Virus (HIV) infection since they can occur in up to 50% of HIV-infected patients and in up to 80% of patients at the AIDS stage (<200 CD4+ T lymphocytes)." (PMID 36143891, 2022). "Participants with ESKD were older, less likely to be female, and more likely to have had an AIDS-defining illness and developed diabetes or cardiovascular disease; nadir and recent CD4 cell counts were lower, and almost all (94.9%) had hypertension." (PMID 35497797, 2022). "Persistent immune activation, which occurs at the onset of HIV infection and persists in people living with HIV (PLWH) receiving effective antiretroviral therapy (ART), plays a key role in CD4 depletion and AIDS progression." (PMID 35967422, 2022). "People living with HIV-1 and HTLV-2 concomitantly show slower CD4+ T cell depletion and AIDS progression, more frequency of the natural control of HIV-1, and lower mortality rates." (PMID 36366570, 2022). "Binary data were excluded from VBM analysis, such as AIDS diagnosis (CD4 < 200 cells/mm3), HIV viral load < 20 copies/mL, and EFV exposure." (PMID 35288604, 2022). "The adjusted HRs for serious non-AIDS events, comparing CD4/CD8 ratio ≤ 0.4 versus CD4/CD8 ratio > 0.4, varied from 1.39 (95%CI 0.96, 2.02) in non-late to 1.62 (95%CI 1.10, 2.40) in late, and 1.49 (95%CI 0.97, 2.29) in advanced presenters." (PMID 35428209, 2022).
AIDS (continued). "Such immune activation continued to increase after a follow-up of almost 2 years and was higher in patients with a low CD4 nadir, a previous AIDS-defining event, or detectable residual viremia during follow-up." (PMID 35632669, 2022). "Only one case was in the AIDS phase with a circulating viral load of 2,000,000 copies/mL, a CD4+ count of 10/mm3, and a CD4+/CD8+ ratio of 0.02." (PMID 36286201, 2022). "Late ART initiation was defined as a CD4 cell count <200 cells/mm3 or having a clinical AIDS diagnosis at the time of ART initiation." (PMID 35784258, 2022). "Most models represent disease progression as a decline in CD4 + T-cell count, with lower CD4 counts leading to reduced quality of life due to AIDS-related complications and higher mortality rates." (PMID 36459306, 2022). "A 58-year-old male patient, diagnosed with HIV/AIDS in June 2020, during hospitalization, nadir CD4 26 cells, admitted with headache, fever for 1 month, and cervical lymphadenomegaly." (PMID 35321086, 2022). "The mean baseline CD4 was 516.4 cells/uL (8% had Cd4 < 200 cells/uL), and the mean VL was 4.49 log10 (20% had VL > 100,000 cop/mL); 11.4% of patients were in the AIDS stage, and 1.1% had positive HBV surface and core antibodies." (PMID 35336931, 2022). "Both AIDS group and pre-AIDS group were divided according to clinical manifestations and CD4 + T cell count." (PMID 36685491, 2022). "The first guidelines were published in 2002 where a CD4 less or equal to 200cells/mm3 and or an AIDS-related condition was the recommended threshold to start ART among those living with HIV." (PMID 36178934, 2022). "Our study was not powered to explain the association found between hyperglycemia and advanced HIV disease (low CD4 cell count, AIDS diagnosis)." (PMID 36301817, 2022). "For example, repeated counts of CD4 cells are vital to HIV/AIDS monitoring; for instance, low levels of CD4 counts are signs of serious viral load accumulation, disease progression, and the need for therapy intervention." (PMID 34983387, 2022). "A 67-year-old male patient was diagnosed with HIV/AIDS in January 2020 and nadir CD4 32 cells, prompting the initiation of antiretroviral therapy." (PMID 35321086, 2022). "In the present study there was statistically significant association between CD4 cell count and intestinal parasitic infection among HIV/AIDs patients." (PMID 35443715, 2022). "Due to depletion of CD4+ T cells in HIV/AIDS patients, fungicidal cells such as monocytes and macrophages have not received CD4+ T cell help via IFN-γ signaling to become fully activated." (PMID 36557672, 2022). "A total of 45.6% (194/424) of these patients had a mean VL of >10,000, and 29% (41/141) had a CD4 cell count that classified them as having AIDS." (PMID 35468087, 2022). "A case of VBDS has been reported to occur in a patient with AIDS, although it is queried if this was in association with CMV co-infection with low CD4 count." (PMID 35070583, 2022). "AIDS is defined by a CD4+ T-cell count below 200 cells/μL or by the identification of at least one AIDS-defining illness." (PMID 35812431, 2022). "AIDS diagnosis by CD4+ count accounted for 57.1% (n = 24/42) of the total cases among males and 60% (n = 9/15) of the total cases among females." (PMID 35305282, 2022). "PML is associated with conditions of CD4 T cell impairment, including HIV/AIDS and idiopathic CD4 T cell lymphopenia." (PMID 36341713, 2022). "Similar to AIDS-KS, there was a correlation between the CD4 T-cell count and CD4/CD8 ratio at baseline and the severity of the disease." (PMID 35626397, 2022). "We observed a higher risk for AIDS-related death among PLHIV who unaccepted ART, whose baseline CD4 cell count was <200 cell/μL, elderly, and lower educated." (PMID 36339239, 2022). "Among infected subjects, AIDS was less frequent (9.8% vs 15.6% p<0.001) and CD4 cell count was higher (mean of 779 vs 670 p<0.001)." (PMID 35587482, 2022).
AIDS (continued). "Instead, CD4/CD8 ratio was found to independently associate with immune activation and serious non-AIDS events." (PMID 35444646, 2022). "According to the Ministry of Health classification of CD4 cell counts, most patients were in the AIDS stage." (PMID 35042469, 2022). "A higher risk for AIDS-related deaths were observed among PLHIV who unaccepted ART, whose baseline CD4 cell count was<200 cell/μL, older age, and lower educated." (PMID 36339239, 2022). "The proportion of HERV reads was increased in AIDS patients with lower CD4+ counts than in HIV-infected subjects with high CD4+ counts." (PMID 35215871, 2022). "These kinds of ulcers are generally observed in severely immunosuppressed AIDS patients (T CD4+ ≤100 cells/μL)." (PMID 36143891, 2022). "In univariable analysis, SCT, age, sex, prior AIDS, lower recent and nadir CD4 cell counts, hepatitis B, anti–hepatitis C virus, diabetes, hypertension, cardiovascular disease, and APOL1 status were associated with eGFR <60 ml/min per 1.73 m2." (PMID 35257059, 2022). "The low frequency of CXCR4 use was not surprising as virus CXCR4 use has previously only been reported from HIV-2 infected individuals with clinical symptoms of AIDS or low CD4+ T-cell counts." (PMID 36366545, 2022). "It is well established that HIV-1 induces a progressive and steady loss of CD4+ T cell count, leading to the impossibility of containing HIV infection, which is characteristic of HIV pathogenesis and culminates in AIDS progression." (PMID 35215997, 2022). "The samples were tested with the avidity assay and subsequently corrected for false recency with the RITA algorithm of the ECDC, that includes the clinical data of AIDS-defining illness, CD4 count, and viral load." (PMID 36304001, 2021). "The majority (54.5%) had received an AIDS diagnosis in their lifetime, had CD4 counts >500 cells/mm3 (58.2%), and reported undetectable viral loads (90.8%)." (PMID 33614590, 2021). "High morbidity and mortality are frequently observed among hospitalized HIV/AIDS patients, particularly having CD4 count ≤100 cells/μl." (PMID 33531906, 2021). "While nearly all PELs develop in the setting of AIDS, patients often have more than 100 CD4+ cells/μL." (PMID 33411730, 2021). "The gold standard diagnostic criteria of the World Health Organization (WHO) for AIDS are CD4+ T-cell count and HIV viral load." (PMID 34881074, 2021). "This aberrant immune activation and inflammation are considered an accelerator of non-AIDS-related events and one of the driving forces of CD4+ T cell depletion." (PMID 34631899, 2021). "In Addition, we extended the base model to recapitulate the oscillating decline in CD4 cells and rapid viral increase after immune escape, characteristic of onset of AIDS and disease progression in some of the macaques in our study." (PMID 34691023, 2021). "Sub-distribution hazard ratios (sHRs) for AIDS-related mortality with baseline CD4+ cell counts and ART initiation time were determined using a competing risk model." (PMID 34592916, 2021). "One of the notable features of HIV pathogenesis is CD4+ T-cell depletion, which is observed during not only the late/AIDS stage but also the early stage of HIV-1 infection; the level of CD4+ T-cell depletion is associated with the plasma VLs." (PMID 33924786, 2021). "This indicates that TCM can increase the CD4+T cell count among patients with HIV/AIDS who have a baseline CD4 count of <350 cells/mL." (PMID 34881074, 2021). "In particular, a low CD4 nadir, previous AIDS-defining conditions and residual viremia have been identified as risk factors for immune activation." (PMID 34458287, 2021). "Then, it was not able to assess factors associating with the pooled prevalence of thrombocytopenia and leucopenia in HAART user participants such as clinal stage of AIDS, CD4 T cell count, type of HAART regimen, and duration of HAART regimen." (PMID 34543340, 2021).
AIDS (continued). "Majority of the HIV/AIDS patients with available CD4 counts were severely immunosuppressed (CD4 count: median, 53 cell/mm3, IQR 16–126; CD4 < 200 cell/mm3: 88.5%)." (PMID 34947017, 2021). "A recent study revealed that an elevated level of the chemokine (C-C motif) chemokine ligand 18 (an M2 macrophage marker) corresponded to a low number of CD4+ T cells in AIDS patients with antiretroviral therapy." (PMID 34072421, 2021). "We observed 10 MCL, 9 ML, and one MCL with visceral involvement and inaugural skin lesions in a patient with AIDS (CD4 count 67/mm3)." (PMID 34644288, 2021). "Immune status in patients with HIV/AIDS was generally poor with a median absolute CD4 T cell count of 70/μl (range 17–314/μl; norm: 300–2200/μl) and a median CD4/CD8 ratio of 0.12 (range 0.03–0.24, norm: 0.7- 2.8)." (PMID 33613439, 2021). "HIV-1, which primarily infects immune cells, in particular T lymphocytes (CD4+, CD8+), is identified as the causative agent of acquired immunodeficiency syndrome (AIDS), which leads to opportunistic infections and diseases." (PMID 34956210, 2021). "The lowest abundance of pegivirus was observed in AIDS patients (CD4 < 200), even though they had the highest overall plasma viral abundance." (PMID 33952659, 2021). "Covariates included pregnancy outcome (born alive vs. others); AIDS diagnosis prior to delivery; CD4, age, HIV‐1 RNA and cART regimen at first delivery and CCASAnet country." (PMID 34021715, 2021). "The high mutation rate of HIV, immune exhaustion and the loss of CD4+ and CD8+ cells make further immune responses ineffective with subsequent progression to AIDS." (PMID 34025935, 2021). "The CD4+ T-cell count at the time of initial cART treatment of patients with HIV/AIDS affects the CD4+ T-cell count recovery and the function of the CD4+ T cells after receiving cART." (PMID 34326884, 2021). "Disease progression from HIV to AIDS in untreated individuals often occurs over a period of 8-10 years, with an inexorable, virus/immune-mediated CD4 T cell destruction." (PMID 34017335, 2021). "Initiating combination antiretroviral therapy can achieve suppression of viral replication and an increase in CD4+ T-cell counts in the majority of patients, resulting in dramatic decreases in morbidity and AIDS-related mortality." (PMID 33684169, 2021). "The CD4+ T-cell count of patients with HIV/AIDS increased to approximately 350 cells/mL more rapidly in the TCM + cART group than in the cART group." (PMID 34326884, 2021). "A 38-year-old man with newly diagnosed advanced acquired immunodeficiency syndrome (AIDS) (CD4 count = 17 cells/mm3) presented with bilateral lower limb weakness associated with bowel and urinary incontinence." (PMID 33950130, 2021). "In a study that used Brazilian HIV surveillance data for the period 2003 to 2006, the prevalence of late entry, defined by the presence of an AIDS defining illness or a CD4 cell count ≤200 cells/mL or an HIV diagnosis at death, was reported at 44%." (PMID 33607975, 2021). "In Guangxi, China, late detection of HIV/AIDS >50.00% and treatment interruptions account for 4.8 per 100 persons a year of the infected cases, and CD4 counts are becoming increasingly necessary for the evaluation of surgical outcomes." (PMID 34616598, 2021). "Multiple factors contribute to the changes in the immune system and progression to AIDS in HIV-infected patients, such as rapid viral replication, increased expression of inflammatory cytokines, and most importantly the loss of CD4+ T cells." (PMID 34336428, 2021). "Lastly, our studies impinged on the field of acquired immunodeficiency syndrome (AIDS) and the human immunodeficiency virus (HIV-1), being the first example of a mediator to associate with the HIV-1 receptor, CD4." (PMID 33791292, 2021).
AIDS (continued). "The significance of the CD4+ T-cell response in inducing protective immunity against C. albicans is indicated by the prevalence of oropharyngeal candidiasis in AIDS (acquired immunodeficiency syndrome) patients whose CD4+ T-cell count is depleted." (PMID 34696267, 2021). "Due to high heterogeneity, subgroup analyses were conducted and stratified by gender, income, AIDS history, study observational years, HIV risk factors and CD4 cell count." (PMID 34070645, 2021). "A retrospective cohort study analyzed the efficacy of TCM therapy on long-term trends in CD4+ T cell counts among patients with HIV/AIDS who were treated with cART over a 14-year period." (PMID 34881074, 2021). "Prophylaxis with trimethoprim-sulfamethoxazole is recommended in patients with a CD4 count below 200 cells/μl, or previous history of AIDS-defining illnesses, such as oral candidiasis, as well as in patients with a CD4 percentage below 14%68." (PMID 34285903, 2021). "Elevated levels of IL8 have been reported in plasma, serum and cerebrospinal fluid in HIV/AIDS patients with CD4+ T cell counts < 350 cells/mm3, a promising marker of the inflammatory process." (PMID 34445956, 2021). "All of the participants were AIDS patients, thus CD4+ T-cell counts for these patients were expectedly low (1–1252 cells/μl) in this study." (PMID 34425768, 2021). "We also observed the interesting phenomenon that only patients with HIV/AIDS who had a baseline CD4+ T-cell count of >500 cells/mL were able to keep a CD4+ T-cell count of >500 cells/mL over most of the time after initiating therapy." (PMID 34326884, 2021). "Some studies used a combination of laboratory-based definitions, such as CD4 count < 200 cells/mm3 or < 350 cells/mm3, and a clinical definition based on the occurrence of an AIDS-defining event in 3 months, 6 months or 1 year following HIV diagnosis." (PMID 33653290, 2021). "An increased plasma viral abundance of main eukaryotic viruses was observed during HIV-1 infection in MSM, especially in AIDS patients (CD4+ T cell counts of <200)." (PMID 33952659, 2021). "A less than 200 CD4 + cells/μL (AIDS category 3) was more frequently found in histoplasmosis group than no histoplasmosis group (95% vs 84%, P = 0.038)." (PMID 34384448, 2021). "On the other hand, an initial viral load of >30,000 copies/mL with a CD4 count of >500 puts a patient at a 76.3% chance of progressing to AIDS within nine years." (PMID 34094761, 2021). "Selective depletion of CD4+ T cells and expansion of CD8+ T cells in HIV infection leads to a low CD4:CD8 ratio, which is associated with increased risk of non-AIDS morbidity and mortality in virally suppressed people living with HIV (PLHIV)." (PMID 34691047, 2021). "They had lower median CD4 cell count and were more likely to have a history of other AIDS‐defining illnesses at cohort entry." (PMID 33405281, 2021). "Among people with all CD4 counts earlier ART (≤4 weeks) increased the risk of IRIS (RD +6%, 95% CI +2% to +10%) and reduced the incidence of AIDS‐defining events (RD −2%, 95% CI −4% to 0%)." (PMID 34289243, 2021). "SIV and SHIV infection recapitulate many aspects of HIV disease, including peripheral CD4 depletion, progression to AIDS, and disruption of gut homeostasis, including depletion of CD4 and T helper 17 (Th17) cells and increased mucosal immune activation." (PMID 34452474, 2021). "We defined late treatment initiation as those initiating treatment with a CD4 < 350 cells/mL or an AIDS-defining event, and treatment initiation with advanced disease as those initiating treatment with a CD4 < 200 cells/mL or an AIDS-defining event." (PMID 33607975, 2021). "Long sleepers, according to actigraphy, were more likely to have a history of AIDS-defining events (OR = 4.45 (1.29–15.28); p < 0.01), with a lower CD4 nadir (OR = 0.66 (0.48–0.91))." (PMID 33429860, 2021).